PDGFRA (platelet derived growth factor receptor alpha)
Diseases named in the same sentence as PDGFRA in open-access papers (continued):
Sharing a sentence is not in itself a finding about the gene and the disease.
melanoma (52 papers, 2005 to 2025). A malignant, usually aggressive tumor composed of atypical, neoplastic melanocytes. "To determine the mechanisms implicated in Snail1 contribution to melanoma growth, we isolated tdTomato+PDGFRα+ cells from BrafV600E-5555 tumours grown in Snail1ME-WT and Snail1ME-KO mice after tamoxifen treatment and performed RNA sequencing." (PMID 37516803, 2023). "On the contrary, we detected SNAI1 expression in melanoma-associated fibroblasts, as indicated by double tdTomato-PDGFRα positive staining." (PMID 37516803, 2023). "PDGFRA is a proto-oncogene, and mutations within its gene are detected in about 5% of melanoma tumors." (PMID 33918692, 2021). "The clinical relevance of these data is indicated by the association of PDGFRα up-regulation in melanoma matched biopsies of BRAF-I +/- MEK inhibitor treated patients with shorter time to disease progression and less tumor regression." (PMID 24732172, 2014). "In this study we provide for the first time both in vitro and in vivo evidence that PDGFRα up-regulation causes BRAF-I resistance of BRAF(V600E) melanoma cells." (PMID 24732172, 2014). "First, PDGFRα expression was up-regulated in 5 out of the 9 matched melanoma lesions with a BRAF(V600E) mutation, surgically removed from patients who had developed BRAF-I resistance." (PMID 24732172, 2014). "PDGFRα up-regulation in human melanoma cells harboring the BRAF(V600E) mutation is shown for the first time to be associated with the loss of their sensitivity to the anti-proliferative and pro-apoptotic activity of the BRAF-I vemurafenib both in vitro and in vivo." (PMID 24732172, 2014). "BRAF inhibitors have been shown to activate the Sonic Hedgehog Homolog pathway in melanoma, which in turn will upregulate PDGFRα, leading to the development of resistance to the inhibitor." (PMID 40574005, 2025). "A recent study revealed the presence of a unique type of MSCs (known as slow-cycling ADAM12+PDGFRα+ MSCs) at tumor edges in melanoma, pancreatic cancer, and prostate cancer mouse models." (PMID 38779660, 2024). "We also observed SNAI1 reactivation in PDGFRα+-CAFs from melanoma lung metastases in Snail1ME-WT mice that was confirmed in BrafV600E/PtenloxP/tdTomato melanomas." (PMID 37516803, 2023). "Recently, three different melanoma CAFs populations have been described and Pdgfrα expression was widely found in the populations enriched at early stages of melanoma progression when our CAFs transcriptomic analysis was performed." (PMID 37516803, 2023). "Here we identified slow-cycling ADAM12+PDGFRα+ mesenchymal stromal cells (MSCs) induced at the tumor margins in mouse models of melanoma, pancreatic cancer and prostate cancer." (PMID 37798557, 2023). "For example, melanoma patients often present with a high population of PDGFRα-positive CAFs, suggesting that resident dermal fibroblasts transitioned into CAFs." (PMID 36671452, 2022). "This is the first report evidencing PDGFRA in melanoma, although its role in triggering VM needs to be further elucidated." (PMID 35621644, 2022). "Previous work in other cancers (e.g., papillary thyroid, breast, and melanoma) has demonstrated PDGFRA signal transduction regulates epithelial-mesenchymal transition (EMT) programs via expression of EMT transcription factors, including SLUG, TWIST1 and SNAIL." (PMID 33603171, 2021). "It is noteworthy that this combination has a significantly greater anti-proliferative and pro-apoptotic effect than either agent alone both in vitro and in vivo also with BRAF-I sensitive human melanoma cells which express PDGFRα." (PMID 24732172, 2014). "To assess the potential clinical significance of our in vitro results, we tested PDGFRα expression in biopsies obtained from 9 melanoma patients treated with BRAF-I or with the novel combination of BRAF-I and MEK inhibitor (MEK-I)." (PMID 24732172, 2014).
melanoma (continued). "Lastly, we describe combinatorial strategies which can be easily translated to a clinical setting to counteract the Shh/PDGFRα mediated BRAF-I resistance of BRAF(V600E) melanoma cells." (PMID 24732172, 2014). "Vemurafenib resistance is overcome in melanoma cells which down-regulate PDGFRα expression following transduction with a PDGFRα-specific shRNA." (PMID 24732172, 2014). "Second, the extent of PDGFRα increase in melanoma lesions, as measured by the increase in the percentage of stained melanoma cells, was associated with the clinical course of the disease." (PMID 24732172, 2014). "Vemurafenib and PDGFRα-I combination markedly inhibits in vitro proliferation and induces apoptosis of melanoma cells with a PDGFRα up-regulation mediated BRAF-I resistance." (PMID 24732172, 2014). "PDGFRα inhibition by PDGFRα-specific short hairpin (sh)RNA and by PDGFRα inhibitors restores and increases melanoma cells' sensitivity to BRAF-I in vitro and in vivo." (PMID 24732172, 2014). "The evidence we provide represents a strong rationale to translate to a clinical setting the combinatorial strategy we have shown to be effective in counteracting the BRAF-I Gli1/PDGFRα-mediated resistance of melanoma cells both in vitro and in vivo." (PMID 24732172, 2014). "Interestingly, comparison of our transcriptomic data with melanoma stromal scRNAseq data showed that tdTomato+PDGFRα+ cells from Snail1ME-WT tumours were enriched in the signatures related to the S1 ("immune") and S2 ("desmoplastic") CAFs subpopulations." (PMID 37516803, 2023). "Similarly, melanoma CAFs also often express high PDGFRα and are predicted to be derived from local normal fibroblasts." (PMID 36671452, 2022). "However, it should be noted that this is the first report evidencing PDGFRA in melanoma, although its role in triggering VM needs to be further elucidated." (PMID 35621644, 2022). "Polymerase Chain Reaction (PCR) and Sanger sequencing techniques were performed to identify the mutational status of BRAF, NRAS, KRAS, NF1, KIT, PDGFRA and SF3B1 on 19 melanomas of the female genital tract, paired with 25 cutaneous melanomas, 18 acral melanomas and 11 melanomas of nasal cavity." (PMID 34102999, 2021). "None of the cases were found to harbor BRAF, NF1 and PDGFRA mutations in melanomas of the female genital tract." (PMID 34102999, 2021). "PDGFRA-expressing cells can be found on tumor-associated fibroblasts infiltrating B16 melanomas but their association with the vasculature has not been investigated." (PMID 25885274, 2015). "Vemurafenib resistance of melanoma cells harboring a BRAF mutation reflects ERK and AKT activation induced by PDGFRα up-regulation, since inhibition of its synthesis by PDGFRα-specific shRNA causes a reduction of ERK and AKT activation and restores sensitivity to BRAF-I." (PMID 24732172, 2014). "The present study demonstrates that human melanoma cells express PDGFRα both in vitro and in vivo." (PMID 24732172, 2014). "Lastly PDGFRα up-regulation has therapeutic implications since BRAF(V600E) melanoma patients with PDGFRα up-regulation may potentially benefit from treatment with BRAF-I in combination with PDGFRα-I or Shh-I." (PMID 24732172, 2014). "Notably, none of the cases were found to harbor SF3B1, NF1, KIT and PDGFRA mutations in cutaneous melanomas, acral melanomas and melanomas of nasal cavity." (PMID 34102999, 2021). "However, in our study, none of the cases were found to harbor NF1 and PDGFRA mutations in melanomas of the female genital tract, as well as in cutaneous melanomas, acral melanomas and melanomas of nasal cavity." (PMID 34102999, 2021). "In melanoma cells resistant to trametinib, few damaging mutations were found including L437F and K438M substitutions in ERBB4 in 11_TRAR, G388R variant of FGFR4, and E36A variant of platelet-derived growth factor receptor alpha (PDGFRA) in 21_TRAR, and E519K alteration of RASGRP4 in 17_TRAR cells." (PMID 31936151, 2020).
melanoma (continued). "Indeed, a trial of cediranib and selumetinib has recently been initiated in solid tumors (NCT01364051) but may be more effective if directed towards melanoma patients with both BRAFV600E mutation and elevated KDR/PDGFRα/β expression." (PMID 26461489, 2015). "As observed in the melanoma, PDPN+PDGFRα+ CAFs were reorganized but still present in similar numbers in tumors lacking ADAM12+ MSCs, and the vasculature displayed increased pericyte coverage and ICAM1 expression." (PMID 37798557, 2023). "In melanomas, genes coordinately expressed with GPC6 were largely those involved in cell adhesion and migration including INHBA, PDGFC, PDGFRA, PPAP2B, SPRX2, TCF4, and TNFAIP6 and ZEB1." (PMID 31199813, 2019). "Various RTK such as IGF1R39, EGFR10,40, PDGFRα/β41,42, ERBB37 or MET29 have been related to drug resistance in melanoma." (PMID 30237393, 2018). "This study provides evidence that in human melanoma cells expressing NRP-1 but devoid of other VEGFRs and PDGFRα expression, an autocrine PDGF-C/NRP-1 loop sustains several characteristics of melanoma aggressive phenotype." (PMID 28977999, 2017). "Furthermore, we found synergistic interaction between cediranib and PLX4720 in non-melanoma BRAFV600E mutant cell lines with expression of KDR/PDGFRα/β family members, suggesting the combination may be effective broadly across BRAFV600E mutant cancers beyond melanoma." (PMID 26461489, 2015). "In addition, in various solid tumors, such as melanoma, a population of slow-cycling ADAM12+PDGFRα+ MSCs exists." (PMID 38779660, 2024). "We also validated SNAI1 expression in PDGFRα+ cells by using PDGFRα-CreERT2-tdTomato reporter mice and confirmed that blocking SNAI1 expression in PDGFRα+ fibroblasts reduced melanoma growth." (PMID 37516803, 2023). "Previous studies demonstrated that PDGF-C, a platelet derived growth factor, binds directly with NRP-1 in melanoma cells, while also stimulating extracellular matrix invasion and p130C phosphorylation in melanoma cells lacking PDGFRα." (PMID 33807778, 2021). "Next, we checked whether the preincubation of A375 melanoma cells with vitamin D derivatives affected the protein level of VEGFR1, VEGFR2, PDGFRa, PDGFRb, or VDR after subsequent treatment with cediranib." (PMID 35004285, 2021). "In melanoma cells expressing NRP-1 but lacking PDGFRα, PDGF-C stimulates extra-cellular matrix (ECM) invasion and induces p130Cas phosphorylation." (PMID 28977999, 2017). "Platelet Derived Growth Factor Receptor-alpha (PDGFR-alpha) potently inhibits melanoma- and endothelium-proliferation and its expression is significantly reduced in melanoma-biopsies, suggesting that melanoma progression eliminates cells expressing PDGFR-alpha." (PMID 27764787, 2016). "It is worth noting that the BRAF(V600E) melanoma cell lines with a PDGFRα up-regulation mediated BRAF-I resistance did not express PDGFRβ and VEGFR2." (PMID 24732172, 2014). "Similarly to PDGFRα inhibition, Shh inhibition by LDE225 restores and increases melanoma cells' sensitivity to BRAF-I." (PMID 24732172, 2014). "Furthermore, LDE225 in combination with vemurafenib down-regulated PDGFRα expression and inhibited ERK and AKT activation in the BRAF-I sensitive and resistant melanoma cells." (PMID 24732172, 2014). "However, Torrent AmpliSeq Colon & Lung Cancer is restricted to colon and lung tumors only and is, therefore, not available for alterations associated with other types of cancers (e.g., cKIT for melanoma and GIST or PDGFRA for GIST are not covered)." (PMID 28404952, 2017). "In conclusion, evidences are presented demonstrating NRP-1 activation by PDGF-C and strongly suggesting that PDGF-C/NRP-1 signaling might be relevant in the metastatic switch of melanoma cells, even in the absence of PDGFRα." (PMID 28977999, 2017). "Similarly to PDGFRα inhibition, inhibition of Gli1 activation by the novel clinically available Shh inhibitor (Shh-I) LDE225 restored (P<0.05) and increased (P<0.05) melanoma cells' sensitivity to BRAF-I." (PMID 24732172, 2014).
melanoma (continued). "Furthermore, these data suggest that PDGFRα may be a useful biomarker to identify patients with BRAF-mutant melanoma who will or will not respond to BRAF-I or combination BRAF-I and MEK-I." (PMID 24732172, 2014). "Additionally, lenvatinib’s secondary antitumor effect is its direct melanoma cytotoxicity, which was not VEGFR-2 dependent and alternatively could be due to effects on FGFRs, PDGFRα, KIT, or RET." (PMID 36821392, 2023).
chronic eosinophilic leukemia (43 papers, 2007 to 2025). "Factor interacting with PAPOLA and CPSF1 (FIP1L1), fused with platelet-derived growth factor receptor α (PDGFRα), has been linked to several hematologic malignancies (hypereosinophilic syndrome, chronic eosinophilic leukemia, systemic mastocytosis)." (PMID 35494081, 2022). "FIP1L1- PDGFRA rearrangements are often associated with chronic eosinophilic leukemia and hypereosinophilic syndromes as well as systemic mastocytosis." (PMID 24669761, 2014). "The FIP1L1/PDGFRA fusion is a hallmark of chronic eosinophilic leukemia and has been studied extensively in EOL-1 cells, but other cell line models are lacking." (PMID 23637631, 2013). "BAY-43-9006 has also been reported to inhibit the oncogenic fusion protein of FIP1-like protein and PDGFRα that causes eosinophilic leukemia; the T674I mutant of this fusion protein is imatinib-resistant." (PMID 20161827, 2008). "FIP1L1 may be implicated in leukemogenic fusion genes, notably in chronic eosinophilic leukemia where it may become fused with platelet-derived growth factor receptor alpha (PDGFRA)." (PMID 32295268, 2020). "Interestingly, hFip1 also comprises the N-terminal part of a fusion protein with platelet-derived growth factor receptor alpha (PDGFRα), which causes 14–60% the incidents of hypereosinophilic syndrome/chronic eosinophilic leukemia." (PMID 23658553, 2013). "Primary eosinophilic disorders are rare in the pediatric population and include chronic eosinophilic leukemia; myeloid/lymphoid neoplasms with rearrangements of PDGFRA, PDGFRB, FGFR1, or PCM1-JAK2; and idiopathic hypereosinophilic syndrome." (PMID 41552084, 2025). "We report a rare finding of chronic eosinophilic leukemia with a rearrangement of the PDGFRA gene in a 53-year-old male patient presenting with symptoms suggestive of vestibular neuritis." (PMID 40454332, 2025). "PDGFRA-related disorders usually present as hypereosinophilic syndrome (HES) of chronic eosinophilic leukemia (CEL)." (PMID 38337573, 2024). "Although no target residual plasma levels are defined in the context of F/P + chronic eosinophilic leukemia, undetectable drug plasma levels can avoid unnecessary sequencing of PDGFRA." (PMID 37122022, 2023). "Among the causes of reactive HE/HES, recent onset of HE/HES should primarily suggest helminthiasis or drug hypersensitivity, as detailed in “Management of FIP1L1::PDGFRA–positive chronic eosinophilic leukemia” section." (PMID 37122022, 2023). "A subset of chronic eosinophilic leukemia (CEL) patients bears mutated and/or fused forms of PDGFRα, which is a receptor TK targeted by ponatinib." (PMID 30423915, 2018). "Gain-of-function mutations in PDGFRα have been found in chronic myeloid leukemia (CML), gastrointestinal stromal tumors (GISTs) and chronic eosinophilic leukemia (CEL)." (PMID 24472312, 2014). "Many of these breakpoints corresponded to known gene fusions, including BCR/ABL1 in CML, FIP1L1/PDGFRA in eosinophilic leukemia, and NPM1/ALK in anaplastic large cell lymphoma (ALCL)." (PMID 23637631, 2013). "However, prior studies on FIP1L1-PDGFRA, a similar gene fusion found in chronic eosinophilic leukemia conserving exon 12 of PDGFRA, suggested a cytoplasmic localization." (PMID 31105873, 2019). "Most cases with PDGFRA gene rearrangements manifest as MPNs, usually chronic eosinophilic leukemia." (PMID 22356850, 2012). "The FIP1L1/PDGFRA (F/P) fusion gene is the most common clonal genetic abnormality of chronic eosinophilic leukemia (CEL)." (PMID 27120808, 2016). "FIP1L1/PDGFRA (F/P) rearrangement is the most common molecular abnormality in chronic eosinophilic leukemia (CEL)." (PMID 27120808, 2016). "The diagnosis of CNL also requires that molecular testing be negative for defining markers of alternate neoplasms including not only the BCR-ABL1 fusion gene but also rearrangements in PDGFRA/B or FGFR1, characteristic of eosinophilic leukemia." (PMID 29440636, 2018).
chronic eosinophilic leukemia (continued). "The most sensitive cell line was the chronic eosinophilic leukemia cell line EoL-1 (IC50 = 59 nmol/L), expressing a fusion gene of Factor Interacting with PAPOLA and CPSF1 (FIP1L1) and platelet-derived growth factor receptor α (PDGFRα)." (PMID 41199836, 2025). "The same way a rare condition known as eosinophilic leukemia, prompted by a chromosomal rearrangement, referred to as FIP1L1-PDGFRA leads to constitutive activation of the PDGFRA tyrosine domain, bringing patients to full remission within months of imatinib treatment." (PMID 29455659, 2018).